C1S (complement C1s)
Diseases named in the same sentence as C1S in open-access papers (continued):
Sharing a sentence is not in itself a finding about the gene and the disease.
tumor (38 papers, 2016 to 2025). "C1S encodes a serine protease crucial to the classic complement pathway, potentially promoting tumor progression through both complement cascade-dependent and -independent manners." (PMID 39179711, 2024). "These particular cancer cells also activated complement pathways and secreted complements such as C1S, C1R, and C3, which facilitated the recruitment of tumor-associated macrophages (TAMs) and T cells." (PMID 38951896, 2024). "A third protein-protein interaction network in the blood cancer patient group includes genes associated with the complement system such as C1S, C3 and C8A, activation of which is mainly associated with pro-tumour effects." (PMID 36649303, 2023). "In particular, tumor cells were shown to produce C1r, C1s, C4, and C3, whereas C1r and C1s were able to take over the tumor-associated macrophages-produced C1q leading to formation of the initiating C1 complex." (PMID 34572075, 2021). "In clear-cell renal cell carcinoma, tumor associated macrophages produce high densities of C1q, which together with tumor cell expressed C1r, C1s, C4, and C3 initiates CP activation." (PMID 33193442, 2020). "Furthermore, the expression levels of F3, PLAT and C1S in tumor cells are linked to sensitivity to specific drugs." (PMID 39179711, 2024). "Given the profound and detrimental prognostic impact of F3, PLAT, and C1S, coupled with their elevated expression in tumor tissues, targeting these genes or their associated pathways may represent a promising therapeutic strategy." (PMID 39179711, 2024). "Additional evidence comes from the knockdown of C1Q components C1R and C1S in cancer cell lines, which slows xenograft tumor growth in mice." (PMID 41473324, 2025). "Subsequent investigation of the hub genes of the MECRGS model at the single-cell RNA level revealed that PLOD2, C1S, and C1R were primarily expressed in tumor cells." (PMID 38951896, 2024). "It demonstrated a notably elevated expression of SERPINA1, RASGRP1, and CFB in tumor tissues, while C1S and TLN2 showed significantly higher expression in normal tissues." (PMID 38751445, 2024). "In contrast, C1s depletion in the tumor cells resulted in the aberrant expression of MHC class I and alleviated the inability of the tumor cells to activate the CD8 T cells." (PMID 38339243, 2024). "Upregulated cathepsin activity (CTSB, CTSD, and CTSZ) and complement pathway (C1QA, C1S) indicated pro-tumor activity by the TAMs in this region." (PMID 38217035, 2024). "C1S triggers complement activation and independently modulates tumor cell phenotype and tumor microenvironment, thereby promoting tumor progression." (PMID 38751445, 2024). "Further, clinical data for ESCC patients were examined based on the TCGA database, which demonstrated a positive correlation between the C1s protein expression and patient factors such as race, residual lesions, and tumor location." (PMID 39071493, 2024). "As confirmed by our experimental results on the GEO databases GSE77861 and GSE161533, C1s expression increased in ESCC tumor tissues." (PMID 39071493, 2024). "Further explorations suggested that C1s facilitates the cancer progression by triggering complement activation, and by modulating the tumor cell phenotype and tumor microenvironment in a complement cascade independent manner." (PMID 36275687, 2022). "In clear cell Renal Cell Carcinoma (ccRCC), tumor cells produce C1r and C1s and use C1q secreted by macrophages, in order to form a functional C1 complex and activate the classical pathway in IgG-containing deposits or on cell-bound pentraxin 3 (PTX3)." (PMID 33113844, 2020). "C1S was also ubiquitously expressed in most cell lines with highest expression in transformed fibroblasts, an important component of the tumor microenvironment." (PMID 31881847, 2019). "This suggests that F3, PLAT, and C1S may enhance immune responses within the tumor microenvironment." (PMID 39179711, 2024).
tumor (continued). "We have previously shown abundant expression of the complement classical pathway C1 complex components, serine proteases C1r and C1s in tumor cells in invasive cSCCs in vivo, whereas the expression of C1r and C1s was lower in cSCCs in situ, actinic keratoses and in normal skin." (PMID 38866870, 2024). "Nevertheless, there is a lack of clinical information and follow-up records related to C1s expression in local patient tumor tissues, which may help further elucidate its clinical significance." (PMID 39071493, 2024). "Therefore, C1s and CP of the complement system can act as an effector of anti-tumor immunity as well as an promoter of the tumorigenic microenvironment in tumor." (PMID 36275687, 2022). "In cSCC, knock-down of C1s, C1r, FB, FH and FI exerts similar effects on the tumor growth." (PMID 33113844, 2020). "Furthermore, knockdown of C1r and C1s suppresses growth and vascularization of cSCC xenograft tumors, and promotes apoptosis of tumor cells in vivo." (PMID 31331124, 2019). "Therefore, C1r and C1s can promote cSCC tumor progression independently of the activation of the classical pathway." (PMID 31331124, 2019). "We note, however, that the expression profile of C1S could possibly support the hypothesis that the observed DC network captures the relationship between tumour cells and infiltrating immune cells." (PMID 31727119, 2019). "Elevated expression of classical pathway components C1r and C1s has been detected in cSCC tumor cells in a culture and the expression levels of C1r and C1s determined with immunohistochemistry have been shown to correlate with tumor progression from AKs to cSCCIS and cSCC in vivo." (PMID 31331124, 2019). "In the reactive astrocytes from the tumor we identified an increased expression of immune associated genes such as CHI3L1, HLA-DRA, CD274, HLA-DRB3, CD37, as well as genes that contributed to proliferation (MKI67, ANXA2) and complement components (C1S, C1R)." (PMID 31186414, 2019). "Then, the complex interaction between the tumor cells secreting the other components of the complement (C1r, C1s, C3, and C4), the MDSCs, and exhausted T lymphocytes leads to proliferation, increased tumor invasiveness, and neoangiogenesis, which ultimately results in tumor progression." (PMID 38339243, 2024). "Therefore, this study suggested that C1s not only took part in the activation of the classical complement pathway cascade but it also promoted tumor cell proliferation and would appear to have a role in conditioning tumor immunogenicity (higher T cell infiltrate and PD-L1 expression)." (PMID 38339243, 2024). "In addition, M2 macrophages synthesize C1q, a complement component that binds to the Fc portion of anti-tumor antibodies and triggers the classical component cascade in the presence of complement components such as C1r, C1s, C4, C2, C3 and C5 produced by tumor cells." (PMID 37622111, 2023). "Our results demonstrate the upregulation of C1R, C1S, C3, IGHM and CFB in poorly differentiated tumours, suggesting activation through the classical pathway." (PMID 40847563, 2025). "Specifically, tumor tissues show increased expression of SERPINA1, RASGRP1, and CFB compared to normal tissues, whereas C1S, SERPINF2, and TLN2 display the opposite pattern." (PMID 38751445, 2024). "We examined C1s expression within EC with The Cancer Genome Atlas (TCGA) database, and explored its expression in ESCC tumor tissues through immunohistochemical and high-throughput sequencing analyses." (PMID 39071493, 2024). "C1r, C1s, C2, C3, C4b were increased in animals treated with combined radiotherapy and anti-C1-INH compared to control tumor, but the down-stream components in the classical pathway were not increased." (PMID 36717781, 2023). "In addition, the overexpression of C1S may be a new escape mechanism to promote tumor progress." (PMID 37006234, 2023).
tumor (continued). "The result showed that the lower mRNA expressions of C3, C5, CFB, and CLU were correlated with more advanced cancer stage, while the lower mRNA expressions of C1S, C8B, CFI, MBL2, and C4BPA were correlated with higher tumor grade in HCC patients." (PMID 34813686, 2022). "Interestingly, C1S, a typical pan-CAF marker, was strongly expressed in HCC tumor cells, suggesting an organ-specific differentiation." (PMID 41228323, 2025). "Given the correlation of C1s expression with residual lesions and tumor location in ESCC, and considering the crucial importance of regulating tumor cell proliferation and apoptosis in cancer treatment, we proceeded to investigate the role of C1s in ESCC cell biological behavior." (PMID 39071493, 2024). "In addition, the mRNA expressions of C1S, C8B, MBL2, CFI, and C4BPA were correlated with tumor grade and prognosis in HCC patients." (PMID 34813686, 2022). "A strong signal for C1q was detected in all tumour specimens examined, while other C components were either absent (C4) or mildly expressed (C1s and C3) suggesting that C1q deposition did not result in the activation of the classical pathway." (PMID 26831747, 2016). "Beside complement regulators and receptors, components normally produced in the liver, as C1q, C1r, C1s, C3 and C5 are locally synthesized and deposited in different tumor types and in the stroma regardless of complement activation, being predominantly tumorigenic in the majority of cancer types." (PMID 40370471, 2025). "Besides, high-throughput sequencing of tumor and adjacent non-cancerous tissues in three ESCC patients also revealed significantly higher C1s expression in tumor tissues (P < 0.01)." (PMID 39071493, 2024). "The amplification of genes such as COL5A1, IDO1, and GOLIM4 were in accordance with their higher expression in tumor samples, whereas no significant change of protein or phosphorylation levels was observed for genes with genomic amplification, such as CD4, CD7, LIME1, UNC93B1, C1S, C1R, or C8G." (PMID 34400640, 2021). "Additionally, the expression of complement C1s in ESCC patients was examined through RT-PCR, immunohistochemistry, and high-throughput sequencing analysis, revealing the elevated C1s expression within ESCC tumor samples relative to adjacent non-cancerous tissues." (PMID 39071493, 2024).
cancer (29 papers, 2016 to 2025). A tumor composed of atypical neoplastic, often pleomorphic cells that invade other tissues. "Our analysis highlighted F3, PLAT and C1S as genes associated with poorer prognosis across various cancers." (PMID 39179711, 2024). "As C1s is activated under various pathological conditions and associated with inflammation, autoimmunity, and cancer development, it is becoming an informative biomarker for the diagnosis and treatment of a variety of diseases." (PMID 36275687, 2022). "FUT5 and C1S have been implicated as biomarkers for differentiation, proliferation, migration, and invasion in other cancers." (PMID 34187466, 2021). "There have been reports of other complement proteins acting intracellularly, such as C1s being recently identified as a prognostic marker in renal cancer, where expression was linked to poorer prognosis, a more aggressive cancer cell phenotype, and possibly increased C4d generation." (PMID 36100972, 2023). "Using multiplex immunofluorescence staining, we confirmed elevated expression of F3, PLAT and C1S in many cancer tissues as compared to paired para-cancerous tissues." (PMID 39179711, 2024). "They recognized a significant expression of C3 and classical pathway components (C1QA, C1QB, C1QC, C1R, C1S, C4A, and C2) in all cancer types." (PMID 38003705, 2023). "Silencing of C1S also resulted in decreased proliferation and viability of cancer cells and strengthened aggregation of T cells." (PMID 36601127, 2022). "Complement C3 with other components of the classical pathway, such as C1QA, C1QB, C1QC, C1R, C1S, C4A, and C2 are found expressed in several cancer cell types." (PMID 34572075, 2021). "For example, C1r and C1s can activate latent MMP-9 by proposing a putative mechanism for C1s in promoting cancer angiogenesis, growth, and metastasis." (PMID 31331124, 2019). "This suggests that the role of F3, PLAT and C1S in cancer immunology may be more complex than initially assumed." (PMID 39179711, 2024). "In summary, our findings provide a bioinformatics perspective on VRGs in pan-cancer, highlighting the pivotal roles of F3, PLAT and C1S, which could potentially be therapeutically exploited and targeted in several cancers, especially in GBMLGG." (PMID 39179711, 2024). "In the TME of ccRCC, TAMs produce C1q, whereas cancer cells synthetize C1r, C1s, C4, and C3." (PMID 38003705, 2023). "In addition, cancer-cell-intrinsic inflammatory tumor subclusters also showed an upregulation of C1R (log2FC = 0.86), C1S (log2FC = 0.46), and C3 (log2FC = 0.48), while the corresponding macrophages showed an upregulation of C1q genes (C1QA, C1QB, C1QC)." (PMID 36973268, 2023). "This may be the case of CO3A1or RPB11, which have so far been identified as involved in the progression of other cancer types, whereas studies on the role of complement C1s or MIPOL1in cancer are still poor." (PMID 33546239, 2021). "We could find one reactive peptide (RAGNFVTVEIQSLVPKK) from the C1S gene which had 7.7% positive rate in cancer group, the other FSP (SLPILFGSLRKQYMYSK) from the same antigen had no reactivity in cancer group at all." (PMID 30478295, 2018). "In another study on UM proteins secreted from cancer cells, it was demonstrated that exosomal proteins (such as Synaptosomal-associated protein 23(SNAP23), Complement C1s subcomponent GN = C1S) that could involve in ECM remodeling, cancer cell migration, and invasion and metastasis." (PMID 36969177, 2023). "C1S is a serine protease involved in the complement pathway and increased expression in basal-like cell lines may contribute to increased immune infiltration within ER− cancers." (PMID 31727119, 2019). "Although both C1S and DCN dominantly mark CAFs alone, C1S was weakly detected in pericytes, but unexpectedly expressed in HCC cancer cells (C1S HCC)." (PMID 41228323, 2025).
cancer (continued). "C3 and its active fragment C3a, downstream effectors of classical complement activation mediated by C1q/C1s/C1r, were time‐dependently increased following AZD4573 treatment, as well as PD‐L1 in KRAS‐mutant cancer cells." (PMID 39254172, 2024). "In particular, C1s/C1r are reported to degrade collagen and are involved in activation of CUB domain containing proteins that regulate many aspects of cancer progression and metastasis." (PMID 27391064, 2016). "Furthermore, our multiplex immunofluorescence staining confirmed the increased protein levels of C1S, F3, and PLAT in cancer tissues compared to their paired para-cancerous tissues." (PMID 39179711, 2024). "The significantly overexpressed sEV proteins in the BC plasma-derived UCT isolates were ALB, COL1A1, CSN1S1, EEF1A2, and RPL3; and the C1S, C5, C7, and CFHR2 sEV proteins in the UCT isolates were the most downregulated proteins in the BC plasma compared to the non-cancer control." (PMID 37895140, 2023). "C1S, FAM20C, KDELR2, and RCAN2 have rarely been reported in cancer." (PMID 33579282, 2021).
infection (12 papers, 2009 to 2024). The state of being infected such as from the introduction of a foreign agent such as serum, vaccine, antigenic substance or organism. "Our results show that plasma levels for PTX3, sMR and, to a lesser extent, C1-INH and C1s/C1-INH, measured soon after infection or symptom onset, are associated with disease severity." (PMID 39027374, 2024). "For complement components, complement C1s, C5, and C8 were significantly increased under the JDm10 infection." (PMID 35893682, 2022). "Results from the microarray validated by Q-RT-PCR, and in selected cases at the protein level, indicate a down-regulation of genes such as C1S, LCN2 and PI3 after infection with N. meningitidis relative to N. lactamica." (PMID 22028815, 2011). "The transcriptome data show over-expression of complement component 1 (C1S), an anti-thrombin peptide (SERPINC1), and fibrinogen beta chain (FGB) during virulent infection." (PMID 19216742, 2009). "Moreover, C3, C5, C2, C1S, C4BPA (genes involved in the complement pathway) and SERPING1 (a regulator of complement activation) were significantly up-regulated, indicating an important role of the complement pathway in this infection." (PMID 34203742, 2021).
infectious disease (2 papers, 2022 to 2023). A disorder directly resulting from the presence and activity of a microbial, viral, or parasitic agent in humans. "Studies have shown that abnormal activation of C1S contributes to the development of autoimmune and infectious diseases." (PMID 37006234, 2023). "It is conceivable that more small molecular, peptide/protein, and antibodies targeting C1s for the treatment of caner, autoimmune, and infectious diseases will be developed." (PMID 36275687, 2022). "Due to the large inhibiting spectrum of C1INH, these findings suggest, but did not prove that activated C1s is an effector, biomarker, and potential therapeutic target of various infectious diseases." (PMID 36275687, 2022).
cardiovascular disease (1 paper, 2025). "Proteins in the complement and coagulation cascades pathway were identified as causal for cardiovascular disease in MR (C1R and C1S) and mediation (18 complement-related proteins mediated the effect of PGST2D_gw and 4 complement-related proteins mediated the effect of the PGSCAD)." (PMID 40032831, 2025).
connective tissue disorder (1 paper, 2023). A disease involving the connective tissue. "Our results indicate that pathogenesis in pEDS is not solely mediated by activation of the complement cascade but by inadequate C1s-mediated degradation of matrix proteins, confirming pEDS as a primary connective tissue disorder." (PMID 36960056, 2023).
neurological disorders (1 paper, 2023). "Specifically, C9, FV, PROS1 and C1s were all significantly up-regulated in NT1 patients compared to controls without neurological disorders." (PMID 37122721, 2023).
C1S also shares sentences with these, for which no sentence is quoted: angioedema (38 papers); acquired angioedema (11); urticaria (4); genetic disorder (3); anaphylaxis (2); bacterial infection (2); breast carcinoma (2); glomerulonephritis (2); lymphoproliferative disorders (2); pneumonia (2); retinal degeneration (2); Sepsis (2); acute respiratory distress syndrome (1); Allergy (1); amyloidosis (1); amyotrophic lateral sclerosis (1); and respiratory failure (1); asthma (1); autoimmune thyroiditis (1); autosomal dominant disease (1); B-cell non-Hodgkin lymphoma (1); brain infarction (1); brain injury (1); breast adenocarcinoma (1); C1Q deficiency (1); carotid atherosclerosis (1); Chronic Lymphocytic Leukemia (1); colon adenocarcinoma (1); common variable immunodeficiency (1); dementia (1).
A further 58 diseases each share a sentence with C1S in 1 paper.